PTPN1 (protein tyrosine phosphatase non-receptor type 1)
Description:
Tyrosine-protein phosphatase which acts as a regulator of endoplasmic reticulum unfolded protein response. Mediates dephosphorylation of EIF2AK3/PERK; inactivating the protein kinase activity of EIF2AK3/PERK. May play an important role in CKII- and p60c-src-induced signal transduction cascades. May regulate the EFNA5-EPHA3 signaling pathway which modulates cell reorganization and cell-cell repulsion. May also regulate the hepatocyte growth factor receptor signaling pathway through dephosphorylation of MET.
Synonyms: PTP1B
Tractability: Small molecule: a structure with a bound ligand is known; a high-quality ligand is known; it has a binding pocket of medium quality; it belongs to a druggable protein family. Antibody: UniProt places it where antibodies can reach, with high confidence; its Gene Ontology location is reachable by antibodies, with high confidence. PROTAC: ubiquitination databases record sites on it; its protein half-life has been measured; a small molecule that binds it is known.
Target class: Tyrosine protein phosphatase; Enzyme; Phosphatase; Protein Phosphatase
Chemical probes: ABBV-CLS-484 (high quality), PD013366
Gene: Protein-coding gene on chromosome 20 (50,510,321 to 50,585,241, forward strand). Ensembl gene ENSG00000196396.
Subcellular location: Endoplasmic reticulum membrane
Subcellular location (Human Protein Atlas): Endoplasmic reticulum; Cytosol
Pathways (Reactome):
Signal Transduction: Insulin receptor recycling; Integrin signaling; Negative regulation of MET activity; PTK6 Down-Regulation
Immune System: Growth hormone receptor signaling; Regulation of IFNA/IFNB signaling; Regulation of IFNG signaling
Cellular responses to stimuli: Turbulent (oscillatory, disturbed) flow shear stress activates signaling by PIEZO1 and integrins in endothelial cells
Gene Ontology:
Molecular function: cadherin binding; enzyme binding; ephrin receptor binding; phosphoprotein phosphatase activity; protein binding; protein kinase binding; protein tyrosine phosphatase activity; receptor tyrosine kinase binding; RNA binding; zinc ion binding; non-membrane spanning protein tyrosine phosphatase activity; insulin receptor binding; phosphatase activity; protein phosphatase 2A binding
Biological process: actin cytoskeleton organization; endoplasmic reticulum unfolded protein response; negative regulation of MAP kinase activity; negative regulation of PERK-mediated unfolded protein response; peptidyl-tyrosine dephosphorylation; platelet-derived growth factor receptor-beta signaling pathway; positive regulation of receptor catabolic process; regulation of endocytosis; regulation of hepatocyte growth factor receptor signaling pathway; regulation of intracellular protein transport; regulation of signal transduction; cellular response to unfolded protein; growth hormone receptor signaling pathway via JAK-STAT; IRE1-mediated unfolded protein response; negative regulation of endoplasmic reticulum stress-induced intrinsic apoptotic signaling pathway; negative regulation of ERK1 and ERK2 cascade; negative regulation of insulin receptor signaling pathway; negative regulation of signal transduction; negative regulation of vascular endothelial growth factor receptor signaling pathway; positive regulation of IRE1-mediated unfolded protein response; positive regulation of JNK cascade; regulation of type I interferon-mediated signaling pathway; vascular endothelial cell response to oscillatory fluid shear stress; cellular response to angiotensin; cellular response to fibroblast growth factor stimulus; and 21 more
Cellular component: cytoplasmic side of endoplasmic reticulum membrane; early endosome; endoplasmic reticulum; endoplasmic reticulum membrane; plasma membrane; protein-containing complex; cytoplasm; cytosol; sorting endosome; endosome lumen; glutamatergic synapse; mitochondrial crista; mitochondrial matrix; postsynapse
Genetic constraint (gnomAD): Loss-of-function variants: 11 observed, 56.71 expected, observed/expected ratio (o/e) 0.19, 90% interval 0.12 to 0.32. The upper end of that interval is the gene's LOEUF score, 0.32, which puts it in group 1 of 6, group 1 being the genes least tolerant of losing a copy. Missense variants: 348 observed, 555.95 expected, observed/expected ratio (o/e) 0.63, 90% interval 0.57 to 0.68. Synonymous variants: 177 observed, 207.21 expected, observed/expected ratio (o/e) 0.85, 90% interval 0.75 to 0.97.
Homologues: Orthologues: chimpanzee PTPN1 (100% identical), macaque PTPN1 (98% identical), pig PTPN1 (89% identical), guinea pig PTPN1 (86% identical), rat Ptpn1 (85% identical), rabbit PTPN1 (84% identical), mouse Ptpn1 (83% identical), dog PTPN1 (72% identical), tropical clawed frog ptpn1 (72% identical), zebrafish ptpn1 (51% identical). Paralogues in human: PTPN2 (53% identical), PTPRF (32% identical), PTPRD (31% identical), PTPRS (30% identical), PTPRE (29% identical), PTPRA (29% identical), PTPRT (29% identical), PTPRM (28% identical), PTPRK (28% identical), PTPRC (28% identical), PTPRB (27% identical), PTPRG (27% identical), and 23 more.
Diseases named in the same sentence as PTPN1 in open-access papers:
PTPN1 is named in the same sentence as 228 diseases in open-access papers, as found by Europe PMC text mining. Sharing a sentence is not in itself a finding about the gene and the disease. The quoted sentences say what the papers report.
Obesity (288 papers, 2006 to 2026). Accumulation of substantial excess body fat. "From a therapeutic perspective, PTPN1/2 represent exciting targets because of their association with numerous diseases, including diabetes, obesity, cancer, and autoimmunity." (PMID 39477543, 2025). "Located on chromosome 20q13.1-13.2, several single nucleotide polymorphisms (SNPs) in the PTPN1 gene have been linked to obesity and diabetes in various populations." (PMID 39238503, 2024). "PTP1B belongs to the intracellular PTPs expressed in various cells and tissues, and its encoding gene, PTPN1, is located in a region associated with insulin resistance and obesity; hence, it is involved in the regulation of the insulin metabolic pathways." (PMID 37686185, 2023). "PTPN1 is a risk-factor gene linked to diabetes and obesity, which has a direct involvement in the insulin and leptin signaling pathways, and that mice lacking this gene were resistant to weight gain and intolerant to glucose." (PMID 34220925, 2021). "The aim of the present study was to further investigate the contribution of common PTPN1 polymorphisms to the risk of T2D and obesity, and to the variability of quantitative metabolic traits in the French population." (PMID 16677372, 2006). "In this study, we investigated the effect of PTPN1 genetic variation on susceptibility to T2D and obesity, and also on quantitative metabolic parameters." (PMID 16677372, 2006). "Only a few association studies between PTPN1 gene variants and obesity status have been reported previously." (PMID 16677372, 2006). "PTPN1 gene variants have been inconsistently associated with T2D, and the aim of our study was to investigate the effect of PTPN1 genetic variations on the risk of T2D, obesity and on the variability of metabolic phenotypes in the French population." (PMID 16677372, 2006). "Furthermore, we concentrated on PTPN1 due to the substantial body of research indicating that PTPN1 variants are associated with obesity, diabetes, and insulin resistance." (PMID 40458121, 2025). "PTPN1/2 are well characterized as regulators of leptin and insulin signaling, and their dysregulations have been linked to metabolic disorders, including diabetes and obesity." (PMID 39477543, 2025). "In line with this notion, mutations in PCa that activate PI3K (such as prostate-specific Pten loss) prime or promote obesity-driven PCa aggressiveness in conjunction with other signalling pathways, such as loss of Ptpn1, IL6/pSTAT3 signalling activation or Pml co-deletion." (PMID 38969865, 2024). "PTPN1 can also regulate food intake and energy expenditure by inhibiting leptin signaling in the hypothalamus, and a hypothalamus-specific loss of PTPN1 exacerbates diet-induced obesity in female mice." (PMID 38338442, 2024). "Since PTP1B-deficient mice are protected from diet-induced obesity and hepatic steatosis, the upregulation of Ptpn1 might, conversely, not protect against hepatic steatosis and could potentially contribute to its development." (PMID 39600697, 2024). "We also investigated the potential contribution of the 14 common PTPN1 SNPs to obesity risk." (PMID 16677372, 2006). "Obesity case-control association study of the 14 PTPN1 SNPs and haplotypes." (PMID 16677372, 2006). "In our study, PTPN1 variants showed moderate association with T2D and obesity." (PMID 16677372, 2006). "According to reports, PTPN1 is involved in the development of many diseases, including obesity, diabetes, cancer, and cardiovascular disease." (PMID 37884566, 2023). "Several studies identified PTPN1, a major negative regulator for insulin receptor signaling, as an ideal therapeutic target for intervention in type 2 diabetes and obesity." (PMID 35449053, 2022). "Protein tyrosine phosphatase 1B (encoded by PTPN1) is recognized as a potential therapeutic target for the treatment of diabetes, obesity and cancer." (PMID 34606417, 2021).
Obesity (continued). "It is well established that the protein tyrosine phosphatase PTPN1 directly regulates the insulin and the leptin signaling pathway, making it a promising therapeutic target for type II diabetes and obesity." (PMID 31527306, 2019). "Over expressing in PTPN1 (encoding Protein tyrosine phosphatase 1B, PTP1B), a protein tyrosine phosphatase (PTP) that plays an overall positive role in insulin signaling, is linked to the pathogenesis of diabetes and obesity." (PMID 23774838, 2013). "In humans, several linkage signals with T2D, BMI, fat mass and energetic intake were reported at this locus in different populations, further supporting PTPN1 candidacy in T2D and obesity." (PMID 16677372, 2006). "The disruption of the PTPN1 gene in mice results in increased insulin sensitivity, resistance to diet-induced obesity and enables normalization of blood glucose levels." (PMID 16677372, 2006). "PTPN1 is considered a critical molecule in mediating insulin resistance and obesity in females." (PMID 40458121, 2025). "Another potential target is Protein Tyrosine Phosphatase 1B (PTP1B), an intracellular protein tyrosine phosphatase expressed in various cells and tissues, with its encoding gene PTPN1 located in a region linked to insulin resistance and obesity." (PMID 39944202, 2025). "Protein-tyrosine phosphatase 1B (PTP1B, encoded by PTPN1) is a physiological regulator of glucose homeostasis and adiposity and thus, has been considered a drug target for the treatment of obesity and diabetes." (PMID 39796132, 2024). "Consequently, PTPN1 inhibitors are potential candidates for the treatment of metabolic diseases, including but not limited to fatty liver, obesity, type 2 diabetes and cardiovascular disease." (PMID 39289804, 2024). "The liver proteins INSR, PTPN1, and ENPP1 are associated with diabetes mellitus type 2 and obesity." (PMID 35259090, 2022). "Whereas knockout of Il-1r1 gene causes leptin resistance and obesity, Ptpn1 knockout results in negative energy balance, protection from weight gain and improved insulin sensitivity." (PMID 29371411, 2018). "Therefore, inhibition of PTPN1 has been proposed to be a potential therapy for obesity, insulin resistance and type-2 diabetes mellitus." (PMID 29088862, 2017). "PTPN1 is a negative regulator of the insulin-PI3K/Akt signaling pathway and is considered a potential therapeutic target for metabolic syndrome, obesity, and diabetes." (PMID 38338442, 2024). "In recent years, the protein tyrosine phosphatase 1B (PTP1B; also known as PTPN1) has emerged as a critical regulator of multiple signaling networks involved in human disorders, such as obesity, diabetes, and cancers." (PMID 36009418, 2022). "Although BVT 948 may be targeting several phosphatases, it exhibits greater efficacy against some PTPs, including PTP1B (PTPN1) and SHP-2 (PTPN11), that are drug targets for cancer, diabetes and obesity." (PMID 26061731, 2015). "Protein-tyrosine phosphatase 1B (PTP-1B), also called protein tyrosine phosphatase non-receptor type 1, is a member of the protein tyrosine phosphatases (PTPs; EC 3.1.3.48) family that plays a role in controlling T2D and obesity." (PMID 34502417, 2021).
diabetes (264 papers, 2007 to 2026). "Patients with type 2 diabetes mellitus display elevated levels of tyrosine phosphatase 1B (PTPN1), and membrane IR-associated glycoprotein PC-1 (ENPP1), which downregulate IR phosphorylation and insulin signal transduction." (PMID 39199273, 2024). "The PTPN1-encoded PTP1B is a well-established protein crucial in intervening in diabetes, and it is also in the predicted targets associated with AD." (PMID 38612872, 2024). "The PTPN1 gene, which encodes PTP1B, is located in 20q13, a genomic region that is linked to insulin resistance and diabetes in human populations from different geographical origins." (PMID 29348454, 2018). "Protein coded by PTPN1, a tyrosine phosphatase kinase gene is a negative regulator of insulin signalling and has been reported to be associated with diabetes mellitus." (PMID 19997558, 2009). "The association between PTPN1 and IR is further supported by various findings that link PTPN1 to IR and diabetes in humans." (PMID 39289804, 2024). "In humans, protein-tyrosine phosphatase 1B (PTP1B), encoded by protein tyrosine phosphatase nonreceptor type 1 (PTPN1), is known to act as a distinct regulatory role in various diseases, such as neurodegenerative diseases, liver disease, cancer, and diabetes." (PMID 36741874, 2023). "With these studies, PTPN1 has become an attractive therapeutic target of diabetes and obesity." (PMID 29021559, 2017). "From this diabetic nephropathy sub-network module we have proposed the two putative interactions of PTPN1 with EGFR and CAV1 which have been highlighted for the first time in diabetes condition." (PMID 19997558, 2009). "Previously, several authors of the current study performed a crystallographic fragment screen of the archetypal protein tyrosine phosphatase, PTP1B (also known as PTPN1), a highly validated therapeutic target for diabetes, cancer, and neurological disorders that has also been deemed ‘undruggable’." (PMID 36881464, 2023). "The upregulation of Ptpn1 in tissues and cells inactivates protein tyrosine kinase (PTK), blocks the effect of insulin on binding to insulin receptors and dephosphorylation of tyrosine residues on insulin receptors substrates, leading to insulin resistance and finally to diabetes." (PMID 37033250, 2023). "This study shows that overexpression of the G0S2 gene aggravates liver insulin resistance of mice through upregulating P-Foxo1, Socs3, and Ptpn1 and downregulating Gstp1 and Ppar-γ, which demonstrates that G0S2 may be a potential target gene for the treatment of NAFLD, obesity, and diabetes." (PMID 37033250, 2023). "Thus, elucidation of the functional mechanism of PTPN1 may help to understand the JNK-dependent cell death, which is a prominent feature in several diseases, such as cancer, diabetes, inflammatory diseases, and neurodegenerative diseases." (PMID 29021559, 2017).
Insulin resistance (240 papers, 2004 to 2026). Increased resistance towards insulin, that is, diminished effectiveness of insulin in reducing blood glucose levels. "PTPN1 found from the network study is linked to the common network pathway and modulates insulin resistance through Jak-Stat, insulin receptor substrates (IRS1 and IRS2) and leptin signaling pathway." (PMID 30674322, 2019). "The same group evaluated SNPs and haplotypes of PTPN1 for association with quantitative glycaemic traits in Hispanic American subjects from the Insulin Resistance Atherosclerosis Study Family Study (IRASFS)." (PMID 16677372, 2006). "Among the top 30 pathways, insulin resistance was top‐ranked and involved in the PTPN1‐INSR‐PI3K‐AKT signalling pathway." (PMID 39289804, 2024). "It is reported that an upregulation of PTPN1 can reverse glucose uptake capacity in gestational diabetic patients, improving their insulin resistance." (PMID 38338442, 2024). "PTPN1 is of particular interest, since it encodes PTP1B, a negative regulator of the insulin receptor signaling and the vascular endothelial growth factor A (VEGFA), contributing therefore to both insulin resistance and endothelial dysfunction." (PMID 34722683, 2021). "In the hypothalamus, metabolism enhancing TTR expression was upregulated, and the PTPN1 level denoting insulin resistance was downregulated, while NPY, AGRP, POMC, CART levels denoting leptin resistance showed a normalizing trend." (PMID 32943760, 2021). "Insulin resistance score, glycemic parameters, and their correlation with PTPN1 expression during ICU stay." (PMID 31737637, 2019). "Despite decreased AKT2 mRNA at week 2 (−28.6%, P = 0.002) and increased PTPN1 mRNA at week 24 (+50.3%, P = 0.016) suggesting insulin resistance, clinical insulin sensitivity [by homeostasis model assessment (HOMA-IR)] was unchanged." (PMID 27516476, 2016). "In addition, it has been reported that mice harboring a germline deletion of Ptpn1 were protected against high-fat diet induced insulin resistance, weight gain, and hepatic steatosis." (PMID 35615361, 2022). "A positive significant association of ff carriers of VDR was also shown (FokI polymorphism) (P = 0.02) and negative association of 148insG carriers of PTPN1 (148insG polymorphism) (P = 0.041) with insulin resistance index." (PMID 26587547, 2015). "Notably, Grb-14 (GRB14) and PTP1B (PTPN1) are known molecular constituents of insulin resistance and development of PTP1B inhibitors for therapeutic modulation of insulin sensitivity is an active field of research." (PMID 20815942, 2010). "Overall, the study demonstrates that farrerol alleviates insulin resistance and hepatic steatosis of MAFLD by targeting PTPN1." (PMID 39289804, 2024). "Several protein tyrosine phosphatases (PTPs), particularly PTPN1, PTPN2, PTPN6, PTPN9, PTPN11, PTPRS, and DUSP9, are involved in insulin resistance." (PMID 37374154, 2023). "Based on the pathway enrichment analysis, targets (INSR, PTPN1, PPARA, PPARG) from two of the most significant pathways, Insulin resistance, and PPAR signaling pathway, were selected for further experimental validation." (PMID 34579756, 2021). "In the validation of pathways, key targets (INSR, PTPN1, PPARA, and PPARG) from two of the most significant pathways in pathway enrichment analysis, Insulin resistance, and PPAR signaling pathway, were selected." (PMID 34579756, 2021). "The increased PTPN1 and STAT5A in the lymphocytes of umbilical core blood in GDM mothers are proposed to contribute to offspring insulin resistance." (PMID 29088862, 2017). "In our earlier investigations, we demonstrated that miR-206 has the capacity to improve hepatic insulin resistance, promote glycolysis, and inhibit gluconeogenesis by targeting Ptpn1 (protein tyrosine phosphatase non-receptor type 1)." (PMID 38866328, 2024). "Notably, IL6, NFKBIA, NFKB1, NOS3, PTPN1, PIK3R1, and STAT3 (members in the enriched WGCNA module) have been shown to alter insulin resistance." (PMID 33005175, 2020).